KRAS (KRas proto-oncogene, GTPase)
Diseases named in the same sentence as KRAS in open-access papers (continued):
Sharing a sentence is not in itself a finding about the gene and the disease.
cancer (continued). "Reactivation of signaling pathways, particularly through EGFR, is a key resistance mechanism in KRAS-mutant cancers." (PMID 41362725, 2026). "Yet, cancers driven by oncogenic KRAS, HRAS, or NRAS remain strongly SHOC2-dependent, suggesting that these weaker complexes contribute to tumorigenesis." (PMID 41519889, 2026). "Kirsten rat sarcoma viral oncogene homolog (KRAS), encoded by the KARS gene, is closely linked to cancer development and progression, thus emerging as a highly promising target for antitumor drug development." (PMID 41497405, 2026). "Orthologues of RAS were originally discovered in cancer-causing viruses in rats, leading to the identification of three endogenous human RAS genes, NRAS, KRAS, and HRAS." (PMID 41535418, 2026). "Here, we found that both sotorasib and adagrasib promoted topoisomerase IIα (Topo IIα) proteasomal degradation in KRAS G12C-mutant cancer cells and induced DNA damage and apoptosis." (PMID 41697749, 2026). "In this study, we conducted a comprehensive analysis of KRAS E4 alternative splicing patterns across multiple cancer types." (PMID 41368203, 2026). "Outlining the current state of KRAS therapy and the remaining research gaps pertaining to these deadly cancers is crucial for the development of future therapeutics." (PMID 41892176, 2026). "KRAS activates cellular pathways that increase the production and transport of fatty acids into cancer cells." (PMID 41481753, 2026). "Scatter plots of UCS cancer tissues confirmed positive correlations between PSI values of KRAS E4 and mRNA expression levels of RBM47 and PTBP1." (PMID 41368203, 2026). "Among the most prevalent mutations in NSCLC, epidermal growth factor receptor 1 (EGFR) and Kirsten rat sarcoma (KRAS) alterations play a key role in cancer progression and patient survival." (PMID 41995791, 2026). "Due to mutations in oncogenes such as Kirsten Rat Sarcoma Viral Oncogene (KRAS), cancer cells can adapt to stress-induced conditions." (PMID 41942421, 2026). "This exclusion pattern of KRAS E4 in cancer cell lines likely explains why most previous studies have mainly focused on the KRAS4B splicing isoform." (PMID 41368203, 2026). "The SHP2 inhibitor JC-010a eliminates RTK/SHP2-mediated resistance to selumetinib in KRAS-mutant cancers." (PMID 41362725, 2026). "Mutations in RAS oncogenes (KRAS, HRAS, NRAS) are among the most common genetic alterations in human cancers." (PMID 41822354, 2026). "Understanding the oncogenic activities of mutant KRAS is crucial for identifying mechanisms of cancer development and progression." (PMID 41368203, 2026). "For example, KRAS inhibitors have been reported to enhance cancer cell antigen processing, antigen presentation to T cells, and reprogram tumor-associated myeloid cells to assist cancer-specific T cells to traffic and function within tumors." (PMID 42001483, 2026). "KRAS and NRAS were mainly altered by mutually exclusive canonical hotspots of missense mutations described in carcinomas." (PMID 41057685, 2026). "Oncogenic KRAS and NRAS mutations are common in hematologic malignancies, but how they signal is less well characterized than in carcinomas." (PMID 41542462, 2026). "Remarkably, we find that KRAS protein is four-fold less stable in hematologic versus carcinoma cells, offering a unique therapeutic opportunity targeting RAS protein stability mechanisms." (PMID 41542462, 2026). "Here, how these molecules are initially discovered and optimized to provide several advanced drug candidates for various KRas‐dependent cancer types are outlined." (PMID 40226972, 2025). "Given that KRAS-mutant tumors with elevated HBP activity rely on this pathway for survival, HBP enzymes, particularly GFPT, present a promising targetable vulnerability in KRAS-driven cancers." (PMID 40830088, 2025). "Our present results proved that KRASmut/ABHD17C axis–mediated ALOX15B downregulation was functionally and clinically relevant to KRAS‐mutant cancer pathogenesis." (PMID 40569151, 2025).
cancer (continued). "While recently developed KRAS inhibitors, such as sotorasib and adagrasib, mark an important milestone—especially for KRASG12C-mutated cancers—their efficacy in CRC remains limited." (PMID 39941797, 2025). "Another marker of poor survival in cancer patients is KRAS, a proto-oncogene, and members of the RAS family of small GTPases." (PMID 40362524, 2025). "To investigate the therapeutic potential of blocking the activity of REGγ-20S as a targeting strategy in pan-KRAS–mutant cancers, we sought to develop a REGγ-20S proteasome inhibitor by docking-based virtual screening." (PMID 40091835, 2025). "Activating KRAS alterations occur in approximately one in seven of all human cancers, making it one of the most prevalent oncogenic drivers." (PMID 39711431, 2025). "Subsequently, it introduces the development of current KRAS inhibitors which target certain KRAS mutants in different types of cancer." (PMID 39820726, 2025). "Proto-oncogene KRAS, GTPase (KRAS) is one of the most intensively studied oncogenes in cancer research." (PMID 39786607, 2025). "Although the study did not include a randomized control group, the promising results indicate that combining adagrasib with cetuximab can offer an effective treatment option for patients with KRAS G12C-mutant cancers." (PMID 40940900, 2025). "Mutant KRAS, which serves as a driver in almost 11% to 14% of cancers, remains constitutively activated and leads to the sustained activation of downstream signaling." (PMID 39437162, 2025). "Based on these findings, monotherapy with KRAS inhibitors, or combination therapy with KRAS inhibitors plus cancer immunotherapies such as ICIs, is expected to be highly effective in BTC patients harboring KRAS mutations." (PMID 40499463, 2025). "Other tumor suppressor genes (KEAP1, STK11), which can impair immunotherapy responses in KRAS-mutant cancers, showed slightly increased frequency from baseline to progression." (PMID 40244261, 2025). "Collectively, these results suggest that RLY01 effectively induces apoptosis and inhibits the growth of pan-KRAS–mutant cancer cells from various tissues by blocking the function of the REGγ-20S proteasome." (PMID 40091835, 2025). "Our focus on cancer was on several pathways including EGFR/KRAS signaling, cyclin-dependent kinases, aromatase hormonal treatment therapy, and epigenetics involving DNMT and HDAC." (PMID 40141193, 2025). "There are three major members of this family: HRAS, NRAS, and KRAS, which are structurally similar but differ in tissue distribution and role in cancer." (PMID 41514544, 2025). "Reported knockdown screens have identified a synthetic lethal interaction between CRAF genetic ablation and MEK inhibition in KRAS-mutant cancers." (PMID 41023593, 2025). "The first KRASG12D-selective inhibitor, MRTX1133, demonstrated near 1,000-fold selectivity for inhibiting KRASG12D signaling and KRASG12D-mutant cancer cell growth as compared with KRAS WT." (PMID 40829181, 2025). "IFN-γ priming of patient cancer organoids enhanced HLA-I expression that likely led to the enhanced reactivity of the KRAS G12V–reactive TCR, but the exact mechanisms require further investigation." (PMID 39846249, 2025). "At the protein level, autophagy was reported to be responsible for the reduction of MHC I in PDAC, and a similar phenomenon has been observed in many other KRAS mutant cancer cell lines, except for the CRC cell line." (PMID 40611261, 2025). "Depleting USP25 expression in cancer cells increases ubiquitination and proteasomal degradation of KRAS, leading to the suppression of its downstream MAP kinase pathway and cell proliferation." (PMID 40473213, 2025). "Given their critical carcinogenic functions, significant progress has been made in developing KRAS inhibitors for cancer treatment." (PMID 39820726, 2025). "These pan-KRAS inhibitors directly target the “OFF” state of KRAS and result in potent antitumor activity in preclinical models of cancers driven by KRAS-mutant proteins." (PMID 39711431, 2025).
cancer (continued). "Ongoing efforts to elucidate and overcome the various mechanisms of primary and acquired resistance to KRAS inhibitors offer a promising path forward for combating KRAS-driven cancers." (PMID 40082410, 2025). "Ongoing research is focused on innovative approaches to overcome these obstacles and improve outcomes in patients with KRAS G12D-driven cancer." (PMID 40597785, 2025). "It is therefore conceivable that KRAS WT–amplified cancers will have high levels of GDP-bound WT KRAS available for binding of KRAS “OFF” inhibitors, such as BI-2493 and BI-2865." (PMID 39711431, 2025). "Another candidate from Moderna, mRNA-5671 (V941), is a therapeutic cancer vaccine targeting KRAS-positive cancers, including CRC." (PMID 40733666, 2025). "Oncogenic mutations like KRAS, MYC, AKT can increase electron flow through the ETC, enhancing ROS production and creating a feedback loop that sustains the cancer phenotype." (PMID 40734168, 2025). "The results are further discussed for the implication of precision delivery of therapeutic and imaging agents to KRAS‐mutant cancers." (PMID 39951277, 2025). "This reprogramming creates a state of heightened metabolic dependency and reduced flexibility, rendering KRAS mutant cancer cells vulnerable to disruptions in key metabolic pathways." (PMID 40563591, 2025). "For example, the p110α H1047L (FIS = 2.04) and KRas G12D (FIS = 3.52) mutations were predicted to be neutral and low impact, respectively, despite their well-known association with cancer." (PMID 40832239, 2025). "On the other hand, STK33 has been identified as a survival factor in KRAS-mutant cancers, stabilized by the HSP90/CDC37 complex." (PMID 41009685, 2025). "Oncogenic KRAS significantly impacts metabolism progresses across various pathways, with the regulation of glucose metabolism intermediates being dominant in most cancers." (PMID 41184283, 2025). "Together, these data strongly support the notion that USP25 promotes cancer cell growth, through (at least partly) stabilizing KRAS expression." (PMID 40473213, 2025). "Cancer metabolism is key to survival, and in PDAC, KRAS mutations drive a distinct metabolic program centered on aerobic glycolysis." (PMID 40805153, 2025). "Through a screening experiment, we identified an innovative REGγ-20S proteasome inhibitor, RLY01, that contributes to the treatment of KRAS-mutant cancers." (PMID 40091835, 2025). "Research has demonstrated that ROS can oxidize cysteine residues to activate the three most prevalent oncogenic switch genes (HRAS, NRAS, and KRAS) in human cancers, ultimately influencing tumorigenesis." (PMID 40563367, 2025). "Sotorasib and Adagrasib, two KRAS G12C inhibitors, have shown efficacy in various cancers, including non-small cell lung cancer (NSCLC)." (PMID 41200180, 2025). "This study shows that the Do‐Cy nanocomplexes are preferentially internalized by cancer cells over other stroma cells via KRAS‐dependent macropinocytosis." (PMID 39951277, 2025). "Specific gene mutations, such as KRAS, NRAS, and BRAF, are known to play a crucial role in the propagation of both cancers." (PMID 40447784, 2025). "REGγ is overexpressed in KRAS-mutant cancers and its expression is correlated with specific KRAS-mutant subtypes." (PMID 40091835, 2025). "Genetic depletion of USP25 expression or pharmacological inhibition of the DUB causes decreases in the expression levels of KRAS (WT or mutants) and in the strength of KRAS downstream signaling, resulting in reduced rates of cancer cell proliferation." (PMID 40473213, 2025). "Published reports show ATF3 promotes progression in other cancers and mediates KRAS signaling directly." (PMID 41198649, 2025). "Our integrated analysis, using an ML‐based FS prioritized 70 features able to distinguish colon and pancreatic KRAS‐mutant versus WT cancers with an AUC equal to 0.74." (PMID 40013338, 2025).
cancer (continued). "Among them, SIAIS562055 emerged as a potent SOS1 PROTAC, exhibiting efficacy against not only KRAS-mutant cancer but also BCR–ABL–driven CML, both in vitro and in vivo, with evidence of robust and durable SOS1 degradation and downstream signal inhibition." (PMID 39437162, 2025). "KRAS emerges as a key player frequently entangled in the complexities of oncogenic stress, since it is frequently activated in cancer." (PMID 40527836, 2025). "The Kirsten rat sarcoma viral oncogene homolog (KRAS) gene is among the most frequently altered genes in cancer, and the KRAS protein was long deemed undruggable." (PMID 40960119, 2025). "A major outcome of KRAS activation is metabolic reprogramming, which enhances nutrient uptake and anabolic biosynthetic pathways in cancer cells." (PMID 40830088, 2025). "Taken together, these results suggest that tissue-specific features should not be overlooked, and that a tissue-agnostic approach to treating KRAS G12C-mutant cancers should be avoided." (PMID 40940900, 2025). "Rarer mutations, such as G12A, G12R, G13C, A146T, G719A, and Q61H, contributed to the molecular diversity of KRAS-mutant cancers." (PMID 40502411, 2025). "The dysregulation of this cellular pathway, often driven by mutations in KRAS or PIK3CA common in MSS tumors like SW480, is frequently observed in various cancers including CRC, making it an attractive target for cancer therapy." (PMID 40918508, 2025). "Given the critical role of KRAS in oncogenesis, the development of new drugs targeting KRAS has been a focal point of hundreds of cancer research labs around the world, due to their potential for the selective killing of cancer cells with mutant KRAS." (PMID 41008802, 2025). "In particular, combined inhibition of oncogenic signaling and autophagy is an effective strategy for treating cancers driven by oncogenic KRAS or BRAF." (PMID 40650680, 2025). "Four clinical trials evaluating this combination have commenced, and data obtained so far suggest this approach as a promising route to indirectly target KRAS-mutant cancers (NCT03981614, NCT02022982, NCT03170206, and NCT04615312)." (PMID 40731832, 2025). "KRAS-mutant cancer cells exhibit increased glycolytic flux and increased dependency on glutamine metabolism and on nutrient-scavenging pathways such as autophagy and macropinocytosis, among others." (PMID 40829181, 2025). "Our findings revealed that KRAS also increased H3K9la, thereby facilitating the expression of cancer-related genes and driving malignant progression." (PMID 40707783, 2025). "The finding of homologous TCRs in independent KRAS Q61H-positive cancers suggests a therapeutic opportunity for HLA-matched patients with KRAS Q61H-expressing tumors." (PMID 40165973, 2025). "Our platform’s versatility was validated through the correction of additional cancer-associated mutations in SMAD4, PTEN, and KRAS, demonstrating its broader applicability in dissecting the functional roles of diverse genetic alterations." (PMID 40696461, 2025). "Additional evidence indicates that in KRAS-mutant cancer cells, IRE1 regulates sensitivity to MEK inhibition and to KRAS-mutant inhibition." (PMID 40208872, 2025). "In a recent study, we showed that variant profiles in the PTPN11 and KRAS genes of HHS-affected dogs is similar to that observed in HS samples, suggesting the dysregulation of common signaling pathways in both cancer types." (PMID 40149290, 2025). "Recent research has emphasized the critical role of KRAS in driving metabolic reprogramming in several cancers, including pancreatic, colorectal, and lung cancers." (PMID 40437561, 2025).
cancer (continued). "Although KRAS is one of the most intensely studied oncogenes, much remains to be understood about how it functions as a cancer driver." (PMID 40829181, 2025). "These included some notable oncogenes known to be drivers in the found cancer types, such as PIK3CA in BRCA, BRAF in SKCM, and EGFR in LGG and LUAD, and KRAS across several cancers including PAAD, LUAD and COAD." (PMID 41415395, 2025). "Overexpression of ANO1 and oncogenic KRAS in cancer cells were demonstrated to increase cell proliferation in vivo and vitro." (PMID 40396170, 2025). "Understanding the distinct biological behavior of mtKRAS compared to wild-type KRAS is essential for developing targeted therapies and improving clinical outcomes in KRAS-driven cancers." (PMID 40869940, 2025). "Genomics and lipidomic analysis have identified that de novo sphingolipid synthesis is an essential pathway for immunosuppression in KRAS-driven cancers." (PMID 41184283, 2025). "Efforts to target RAS through synthetic lethality have been unsuccessful, prompting extensive research into alternate anti-cancer strategies directed against KRAS." (PMID 39857784, 2025). "Mechanistically, the combined loss of mutant KRAS and STAT3 disrupts a core transcriptional program of cancer cells critical to oncogenic competence." (PMID 40859018, 2025). "It seems that cancer cells can overcome KRAS mutant inhibition through wild-type RAS and RAF proteins, leading to the reactivation of receptor tyrosine kinase (RTK)." (PMID 40597785, 2025). "Using these small-molecule inhibitors, we show that direct pharmacologic inhibition of KRAS in the inactive “OFF” state results in growth inhibition in KRAS WT–amplified cancer cell lines in vitro and in CDX and PDX models in vivo." (PMID 39711431, 2025). "Among these mutations, the G12C variant is the most prevalent, accounting for 40% of KRAS mutations and occurring in 10–13% of NSCLC, with lower frequencies in other cancers." (PMID 40576713, 2025). "Because of its critical involvement in cancer biology, KRAS is frequently referred to as the Holy Grail of therapeutic discovery and has been claimed to be a key oncogenic driver for drug development." (PMID 40075634, 2025). "This expanded understanding guides the development of more effective targeted therapies against KRAS-driven cancers." (PMID 40862711, 2025). "These molecules can target oncogenic KRAS gene involved in cancer progression, making them particularly valuable in the treatment of various cancers, including lung cancer." (PMID 40625850, 2025). "KRAS serves as a therapeutic target for cancer, but there are only a handful of KRAS gene-targeted drugs due to their “undruggable”." (PMID 40221400, 2025). "The development of PROTAC-based KRAS degraders is another emerging strategy for targeting KRAS-mutant cancers." (PMID 40829181, 2025).